TGFB2 (transforming growth factor beta 2)
Diseases named in the same sentence as TGFB2 in open-access papers (continued):
Sharing a sentence is not in itself a finding about the gene and the disease.
tumor (continued). "We further observed that overexpressing TGFβ2 in triple‐negative breast cancer cells counteracted the inhibitory effects of ezetimibe on tumor cell invasion and metastasis." (PMID 38531630, 2024). "These considerations will enable a more nuanced assessment of the impact of tumor heterogeneity characterized by TAM component and TGFB2/IFN-I activation mechanisms to predict clinical outcomes and to provide biomarkers for stratified analyses based on molecular characteristics of PDAC tumors." (PMID 39457004, 2024). "We obtained similar results in an independent validation dataset of microarray-based mRNA levels for TGFB1, TGFB2, and TGFB3, and their correlated expression with specific transcription factors in tumor specimens from 41 pediatric patients with DIPG (N = 29) or H3K27M-mutant GBM." (PMID 36980562, 2023). "Similar results were obtained in an independent validation dataset of microarray-based mRNA levels for TGFB1, TGFB2, and TGFB3, and their correlated expression with specific transcription factors in tumor specimens from 41 pediatric patients with DIPG (n = 29) or H3K27M-mutant GBM." (PMID 36980562, 2023). "None of the TGFB2 receptors exhibited a lower expression level in tumor samples from GBM patients vs. DIPG/DMP patients to explain the observed lack of prognostic significance of higher TGFB2 mRNA levels in this patient population." (PMID 36980562, 2023). "RNA levels of TGFB2 significantly increased in CAS of non-metastatic tumours more than metastatic ones by RNAseq, a trend that was mirrored by RT-qPCR analysis." (PMID 37391533, 2023). "In addition to influence on functions and proliferation of tumor cells, 5-LO also regulated genes involved in inflammation and the manipulation of the tumor microenvironment among them MCP-1, fractalkine, PDGF, TGFβ2 and integrins." (PMID 36114329, 2023). "Numerous cytokines and chemokines known to enhance stromal activity such as TGFB1, TGFB2, TGFB3, CXCL12, CCL2 and IL-6 were found downregulated in 211F MEF cells, suggesting a potential tumor-promoting function of Y211 phosphorylation through regulation of the secretome in the stromal environment." (PMID 35628489, 2022). "Based on the in vitro transcriptome analysis and validation of “cytokine-cytokine receptor interaction,” “PI3K-Akt signaling pathway” and “MAPK signaling pathway,” we measured the relative protein expression of TGFB2, INHBB, PIK3R3, ITGB8, NTRK, and CACNA1D in tumor tissue." (PMID 36386893, 2022). "Indeed, three of the four CAF index genes (TGFBI, TGFB2 and FN1) appear in the 938 DEG signature that separates C2 from C1 tumours." (PMID 36207323, 2022). "TGFβ2 is involved in the EMT involved in cell migration and angiogenesis, and overexpression of TGFβ2 promotes tumor growth and invasion, therefore its inhibition by arsenate exposure might contribute favorably to treatment efficacy." (PMID 35563174, 2022). "Genes related to cancer pathways were downregulated upon atezolizumab treatment, including angiogenic factors for tumor vascularization (TNK1, AREG and KDR), proto-oncogenes (RET and MET) and tumor cell survival/migration/invasion (CDH1, RARA, WNK2, WNT4A, WNT9A, TGFB2, EGF, and LAMA3)." (PMID 32616706, 2020). "Mechanistically, imperatorin can directly bind with CREB1 and inhibits its phosphorylation and interaction with TGFβ2 promoter, then inactivates extracellular signal‐regulated kinases (ERK) signaling and fibroblasts‐secreted CCL2 to block tumor angiogenesis and metastasis." (PMID 32832354, 2020). "Interestingly, our results reveal a down-regulation of TGFβ1 and an up-regulation of TGFβ2, TGFβ3, Smad4 and RAC1b in treated cells, suggesting that PRP treatment promotes the TGFβ pathway role via a tumour suppressive route." (PMID 31388092, 2019).
tumor (continued). "Yet for RENCA, tumor progression also yielded an overall increase in suppressive myeloid cell (MDSC) density, as well as increased expression of genes that drive monocytic MDSC immunosuppression (NOS2/iNOS, MIF, and TGFβ2)." (PMID 30388137, 2018). "In addition, proteins involved in tumor cells invasion such as CXCL1, CXCL5, and MMP1 were displayed to be expressed and interacted with ICAM-1 and TGFβ2 in the network analysis." (PMID 29966014, 2018). "Sorted CD8+ T cells from PB of healthy donors were cultured in vitro on a plate coated with ICAM-1 Fc chimera to mimic the engagement of ICAM-1-mediated engagement of tumor cells binding to LFA-1 on the surface of CD8+ T cells, in the presence of soluble human recombinant TGFβ2 and anti-CD3." (PMID 29966014, 2018). "Taken together, these results show that DDB2 represses TGFB2 mRNA expression irrespective of tumor types." (PMID 30410671, 2018). "Thus, we demonstrate a novel tumor escape suppressing perforin expression in CD8+ T cells mediated by ICAM-1 and TGFβ2, which can be targeted in combination for cancer immunotherapy." (PMID 29966014, 2018). "Tumor samples 5, 8, 11, 13, and 15 were most consistent with the predicted FRA-1 signature, mirroring the predicted trend 100% of the time for genes other than TGFB2." (PMID 27220889, 2016). "To investigate whether our in vitro findings would be reflected in tumour specimens from CRC and PC, we evaluated the expression of IL6 and TGFB2 in CRC specimens (n = 14) and PC specimens (n = 12) by RT-PCR." (PMID 26503803, 2015). "Sometimes, a very low level of TGFβ2 was detected in SC tumours (two out of the six) without expression of MUC4 (data not shown)." (PMID 14760381, 2004). "Additionally, TGFB2 methylation correlates inversely with numerous T cell receptor (TCR) signaling components—HLA-D molecules, CD3D, CD28, and LCK—all of which are upregulated in the tumor when TGFB2 is weakly methylated." (PMID 40650134, 2025). "This may be explained by SW480 being an MSS tumor that produces GM-CSF (ATCC.org), whereas HCT116 is an MSI tumor that produces immunosuppressive cytokines, such as transforming growth factor β1 (TGFβ1) and TGFβ2." (PMID 40503011, 2025). "Furthermore, CAFs may alter the anti‐tumor immune response through secretion of several immune modulators such as IL6, CCL2, CXCL12, and TGFβ2, which we found to be up‐regulated in CMS4 PM." (PMID 39739693, 2025). "Notably, TGFB1, TGFB2, TGFB3, S100A8, S100A9, IL6, and PTGES secreted by PMN-MDSCs exhibit both protumorigenic and immunosuppressive properties, playing significant roles in promoting tumor growth and evading immune responses." (PMID 41280721, 2025). "TGFB2 gene methylation was negatively correlated with interferon-related pathways and the expression of mRNA for genes involved in the key mechanisms for priming naïve CD8+ T-cells via the presentation of tumor antigens by professional antigen-presenting cells." (PMID 40338274, 2025). "However, our study discovered a novel mechanism for inhibiting tumor metastasis with ezetimibe: inhibiting the migration and invasion of triple‐negative breast cancer cells by suppressing TGFβ2 expression." (PMID 38531630, 2024). "We compared the survival outcomes of non-DIPG DMG patients whose tumor location was outside the pons/brainstem with TGFB2 mRNA expression levels greater than or equal to the upper quartile (TGFB2high) to the treatment outcomes of the remaining non-DIPG DMG patients (TGFB2low)." (PMID 36980562, 2023). "As a first step to address this point, we tested whether increasing the stimulation time by exogenous TGFB2 of JUNB-overexpressing U2OS cells, which would mimic permanent production of this cytokine in an advanced tumor environment, could affect cell proliferation." (PMID 36494864, 2022).
tumor (continued). "For these tumor types, donors with selective copy number gains of IL10 or TGFB2 were found to have a worse overall survival than that of donors without these copy number gains (p = 0.0551 for IL10 in Liver-HCC; p = 0.1 for TGFB2 in Lung-AdenoCA; p = 0.0202 for both IL10 and TGFB2 in Cervix-SCC)." (PMID 34344966, 2021). "Regardless of the tumor type or tumor site, Ly6c1high CAFs (iCAFs) showed enrichment for Il33, Il6, Ccl7, Cxcl1 and Cxcl12 whereas α-SMAhigh CAFs (myCAFs) expressed high levels of Tgfb1, Tgfb2 and Ctgf." (PMID 32455670, 2020). "Gene Ontology analysis of The Cancer Genome Atlas (TCGA) gene expression datasets of ESCC patients with or without lympy metastasis identifies that TGFβ2 is highly enriched in the pathways essential for tumor metastasis and upregulates in the metastatic ESCC tumors." (PMID 32832354, 2020). "However, using TGFβ2 and ICAM-1, we could recapitulate the immunosuppressive microenvironment of the tumor, diminishing 50% of perforin expression on naïve CD8+ T cells." (PMID 29966014, 2018). "Since the gMDSCs derived from metastatic 4T1 tumour-bearing animals were able to suppress the EMT-related genes and also induce distinct set of genes; S100A9, MMP8, S100A8, WFDC21, LYZ2, FPR1, CCL3, TGFb2, we reasoned whether these genes could be specific for metastatic/aggressive behaviour." (PMID 28382931, 2017). "This increase in TGFβ2 may exert several effects upon tumour growth in vivo, however, we saw no direct effects of TGFβ2 or TGFβ2 inhibition upon CAF contractility." (PMID 27563925, 2016). "Thus, nuclear FAK drives the transcription of Ccl5 and TGFβ2, which are required for recruitment and expansion of immuno-suppressive Tregs into SCC tumors, altering the balance between CD8+ T cells and Tregs in favor of tumor tolerance." (PMID 26406376, 2015). "Similarly, TGFB3’s expression may be elevated in PDAC, but its role may not independently drive aggressive tumor biology to the extent that TGFB2 does." (PMID 40650134, 2025). "None of the TGFB2 receptors exhibited a lower expression level in tumor samples from non-DIPG DMG patients (N = 19) compared to the tumor samples from DIPG patients (N = 41) to explain the observed lack of prognostic significance of higher TGFB2 mRNA levels in this patient group." (PMID 36980562, 2023). "Collectively, these results provide evidence showing that imperatorin may inhibit TGFβ2 expression in cancer cells to suppress CAFs‐secreted CCL2 and the subsequent paracrine effect on endothelial cells and cancer cells, therefore, blocking tumor angiogenesis and invasion." (PMID 32832354, 2020). "As global targeting of TGFβ signalling may not be desirable because of its function as a tumour suppressor in normal epithelial cells, strategies targeting TGFβ2 isoform expression may provide the specificity required to block only the pro-metastatic functions of the TGFβ signalling pathway." (PMID 21063401, 2010). "However, the SC tumour samples showed no undetectable TGFβ2 expression." (PMID 14760381, 2004). "The mode of action of TGFB2 is complex in the LGG TME, involving the activation of IFNGR2 pathways, tumor cells, and TAMs independent of the IDHwt genotype of tumors." (PMID 38539537, 2024). "We showed that TGFβ2 expression but not TGFβ1 or TGFβ3 expression is preferentially elevated TNBC cell lines, patient serum and tumour samples." (PMID 38299307, 2024). "Conversely, TGFB2 expression was significantly higher in GH-secreting (4.2-fold, p<0.0001) and PRL-secreting tumor tissue (6.1-fold, p<0.0001), but not in NFA and ACTH-secreting tumor tissue, than in normal pituitary tissue." (PMID 35600354, 2022). "SRGN and TGFβ2 protein expression in TNBC tumor tissues was significantly higher than that in non-TNBC tumor tissues [Luminal A (P<0.001), Luminal B (P<0.05), and HER2 (P<0.01)]." (PMID 28692037, 2017).
tumor (continued). "Finally, despite TGFB2 and TGFBR3 being preferentially expressed in the OC3 tumor group, in clinical samples, both genes were not significantly enriched in the tumor cell type." (PMID 32605311, 2020). "Moreover, when only subjects with tumor recurrence were considered, a significant increase of PAX3d was evident, particularly six months after their enrollment, while MITF-m and TGFB2 levels did not change." (PMID 29156734, 2017). "The significant statistical interaction between TGFB2 and the nine marker genes suggests that TGFB2 is a negative prognostic indicator at low levels of the IFN-I activated genes and TAM marker expression, including the immune checkpoint LGALS9 (upregulated 16.5-fold in tumor tissue; p < 0.0001)." (PMID 39457004, 2024). "Furthermore, absence of 5-LO elevated TGFβ2 expression in HCT-116 cells while MCP-1, fractalkine and platelet-derived growth factor expression was attenuated in U-2 OS cells suggesting that tumor cell-derived 5-LO shapes the tumor microenvironment." (PMID 36114329, 2023). "Although TGFβ2 specifically increased the pool of STP cancer cells in culture, as expected, it did not enhance the tumor progression when the cells were transplanted either subcutaneously or intracranially, as TGFβ2 did not increase the number of LTP tumor-initiating cancer stem cells." (PMID 21246056, 2011).
cancer (239 papers, 2002 to 2026). A tumor composed of atypical neoplastic, often pleomorphic cells that invade other tissues. "Our current bioinformatics analysis reveals that TGFB2 is associated with the lipid metabolic pathway in cancer drug sensitivity databases." (PMID 38914663, 2024). "Epithelial-mesenchymal transition (EMT) is closely associated with the invasiveness and distant metastasis of cancer cells, which can be induced by TGFβ2 via the TGFβ/SMAD signaling pathway." (PMID 39232806, 2024). "The immunosuppressive TGFβ cytokine isoforms contribute to immune evasion strategies promoted by tumors and in a number of cancers, TGFβ2 has been closely implicated in epithelial to mesenchymal transition (EMT), a precursor to the metastatic process." (PMID 35069536, 2021). "IL-6, IL-8, CXCL1, GM-CSF, and TGFβ2 are recognized pro-tumorigenic factors associated with cancer progression." (PMID 30111846, 2018). "In one study, the paracrine function of TGFb2 has been reported in cancer-associated fibroblasts (CAFs)-induced EMT of oral keratinocytes." (PMID 30410671, 2018). "In cancer cells, the TGFB2 and BMP2&4 ligands are implicated with promoting EMT, whereas BMP5 and BMP7 are inhibit basal and/or TGF-β-induced EMT." (PMID 25972361, 2015). "The disruption of the TGFβ2/SMAD pathway is implicated in various cancers." (PMID 37215143, 2023). "IL‐6, CXCL1 and TGFβ2 are known pro‐tumorigenic factors associated with cancer progression." (PMID 34216174, 2021). "Notably, some of the cancer cell lines with TGFB2 or PRDM16 gene hypomethylation also displayed cancer cell linked promoter hypermethylation." (PMID 25606572, 2014). "We compared the distribution of patient characteristics: cancer stage, histological grade, sex, and age, partitioned across four sub-groupings based on TGFB2 and IRF9 mRNA expression levels and TGFB2 and IFI27 mRNA expression levels." (PMID 39457004, 2024). "Cancer Cell Line Encyclopedia (CCLE) database analysis revealed that the mRNA expression of TGFB2 in MCF7 and MDA‐MB‐453 cells was lower than in MDA‐MB‐231." (PMID 38531630, 2024). "In consistency with previous reports, our findings supported the cancer suppressor role of miRNAsTGFβ2 in BC cells via repressing TGFβ2 expression." (PMID 38299307, 2024). "Analyses of the Cancer Therapeutics Response Portal (CTRP) revealed that TGFB2 expression correlated with resistance to gemcitabine in PDAC." (PMID 38914663, 2024). "Glycoprotein-A repetitions predominant (GARP) is a cell surface docking receptor for activating latent TGFβ1, TGFβ2, and TGFβ3, with its expression restricted predominantly to effector Treg and cancer cells." (PMID 38085441, 2024). "While extensive research has been conducted on the role of TGFβ1 in other wasting conditions such as muscle dystrophy, the contribution of TGFβ2 and TGFβ3 to cancer cachexia remains unexplored." (PMID 37701438, 2023). "In turn, miR-191 targets the RNA binding protein HUR and indirectly upregulates transforming growth factor beta 2 (TGFβ2) expression, which leads to upbeat TGFβ signaling and increases the migration of cancer cells." (PMID 37583933, 2023). "To address this issue, we used a particularly well-suited study model consisting of the down-regulation of the TGFB2 gene by the TF Fra-1 in Fra-1-overexpressing cancer cells, as Fra-1 binds to multiple enhancers interacting with the TGFB2 promoter." (PMID 37464380, 2023). "TGFβ defines three subtypes (TGFβ1, TGFβ2, and TGFβ3), of which TGFβ is highly expressed in many cancers, especially those showing high dissemination potential." (PMID 36119489, 2022). "TGFβ2 was significantly negatively correlated with mRNAsi and significantly positively correlated with cancer stem cell markers DCLK1, Lgr5, CD133 and CD44." (PMID 35620459, 2022). "TGFβ defines three subtypes (TGFβ1, TGFβ2 and TGFβ3), among which TGFβ2 is highly expressed in many cancers, especially those tumors that show high transmission potential (Massagué, 1998)." (PMID 35620459, 2022).